STAT3 (signal transducer and activator of transcription 3)
Diseases named in the same sentence as STAT3 in open-access papers (continued):
Sharing a sentence is not in itself a finding about the gene and the disease.
eosinophilia (23 papers, 2010 to 2025). "The hyper-IgE phenotype and clinical features of atopic disease, like dermatitis, food allergy, and eosinophilia, seen in STAT3 deficiency and ZNF341 deficiency are replicated by pathogenic variants in IL6R or IL6ST." (PMID 40040707, 2025). "Eosinophilia is found in over 90% of STAT3-DN patients and is linked to impaired neutrophil function, and the induction of neutropenia with circulating neutrophils decreasing to approximately 700 cells per microliter." (PMID 40040707, 2025). "Severe AD-like phenotype, increased susceptibility to S. aureus infections and eosinophilia are some of the clinical features of this disease, in addition to reduced peripheral Th17 cells (STAT3 is involved in Th17 differentiation cells)." (PMID 31438472, 2019). "Diagnostic markers such as elevated IgE levels and eosinophilia supported the HIES diagnosis, which was further confirmed by the identification of a STAT3 gene mutation." (PMID 38333292, 2024). "In a mouse model of OVA-induced allergic asthma, STAT3 inhibition significantly reduced eosinophilia and neutrophilic as well as blood histamine levels [25••], suggesting mitochondrial STAT3 to be a promising target to prevent mast cell activation and its associated pathology." (PMID 36520269, 2023). "Unbiased single-cell sequencing analysis of controls and SP-CI73T mutants at a time coordinated with peak eosinophilia (14 days) defined heightened inflammatory activation, chemotaxis, and survival signaling (IL-6, IL-4/13, STAT3, Glucocorticoid Receptor, mTOR, and MYC) in eosinophils." (PMID 35571100, 2022). "However, targeted disruption of STAT3 in airway epithelial cells (e-STAT3-/-) showed a significant decrease of airway eosinophilia suggesting an important role for STAT3 in allergic inflammation." (PMID 20169197, 2010). "To test if these mutations might also be associated with persistent eosinophilia, we sequenced known mutation hotspot regions of STAT3 and STAT5B in 153 cases but no variants were seen apart from STAT5B N642H." (PMID 30573779, 2019).
Infertility (23 papers, 2007 to 2026). "This is supported by research showing that impaired STAT3 signalling is associated with infertility or poor pregnancy outcomes." (PMID 40002703, 2025). "Studies have reported that leukemia inhibitory factor (LIF) and its JAK2/STAT3 signaling pathway are among the pathways most closely associated with infertility due to abnormal endometrial receptivity." (PMID 38896093, 2024). "Several previous reports have demonstrated that CE decreases the level of LIF, thus causing the abnormal function of the JAK2/STAT3 signaling pathway, which affects endometrial receptivity and ultimately leads to embryo implantation failure and is a possible pathogenesis of CE infertility." (PMID 38896093, 2024). "Several mouse models deficient in cytokine signaling such as Lif−/− or Stat3−/− show infertile phenotype, but the defects are already found in implantation rates before decidualization, suggesting more fundamental and pleiotropic roles for the signaling downstream." (PMID 27287066, 2016). "STAT3 signaling involving the leukemia inhibitory factor (LIF) is critical for embryo implantation and reproductive fertility, and LIF deficiency is associated with unexplained recurrent abortion and infertility in women and inactivation of STAT3 causes pregnancy failure." (PMID 26681200, 2015). "However in our study, the increased expression of PDIA3 during receptive phase/mid-secretory phase endometrium of infertile women might induce IL-11/STAT3 signalling pathway, which in turn cause proliferation and growth of endometrial cells." (PMID 25405865, 2014). "We investigated the seminal plasma and serum expression profiles of TUG1, MALAT1, miR-483, and miR-141 and their targets TGF-β1 and STAT3 in severe male factor infertility." (PMID 40425698, 2025). "Ablation of STAT3 in murine models results in dysregulation of uterine epithelial remodelling, resulting in aberrant embryonic attachment, infertility and implantation failure." (PMID 38745948, 2024). "We previously reported that mice with eKO of Lifr and Stat3 resulted in infertile phenotypes with abnormal epithelial morphology." (PMID 39587062, 2024). "We previously demonstrated phosphorylation of STAT3 in eutopic endometrium of infertile women with this disorder leading to over-expression of the oncogene BCL6 and stabilization of hypoxia-induced factor 1 alpha (HIF-1α)." (PMID 28754906, 2017). "The down-regulation of STAT3 in chlamydia-infected infertile mice therefore predicts pregnancy failure and infertility observed in these mice." (PMID 26681200, 2015). "The activation of IL‐6/JAK2/STAT1 and STAT3 signaling pathways are found in the hydrosalpinx in infertile patients, indicating that they might be involved in the pathogenesis of hydrosalpinx." (PMID 37382258, 2023). "Stat3-uKO female mice showed infertility due to implantation failure with enhanced estrogenic responses, presenting increased expression of 17β-estradiol (E2) -responsive genes Ltf and Muc1 and persistent epithelial proliferation in the peri-implantation uteri." (PMID 32968170, 2020). "It is also plausible that IL-11 and LIF stimulate pSTAT3 in glandular epithelium but the levels of STAT3 protein may be low in glandular epithelium of some infertile women." (PMID 18047677, 2007). "Reduced IL-11 production and STAT3 phosphorylation may contribute to unexplained infertility in some women." (PMID 18047677, 2007). "Screening via the STRING platform and Cytoscape 3.10.1 software yielded four core targets for ATBC-induced infertility-HSP90AA1, PIK3CA, CASP3, HRAS-and four core targets for icariin treatment-IL6, TNF, STAT3, and INS." (PMID 41898778, 2026). "Female mice lacking Stat3 (Stat3 eKO), Gp130 (Gp130 eKO), or Lifr (Lifr eKO) exhibit infertility due to implantation failure." (PMID 40427591, 2025).
Infertility (continued). "In this context, this study aimed to investigate the seminal plasma and serum expression of TUG1, MALAT1, miR-483, and miR-141 and their networks TGF-β1 and STAT3 in infertile men with non-obstructive azoospermia (NOA) and severe oligozoospermia (SO)." (PMID 40425698, 2025). "However, in Y1138S LEPR-B mutant females in mice, this mutation induced impaired STAT3 signalling with residual STAT5 function, but it did not cause infertility." (PMID 33371230, 2020).
myeloid leukemia (23 papers, 2011 to 2025). A clonal proliferation of myeloid cells and their precursors in the bone marrow, peripheral blood, and spleen. "For instance, in myeloid leukemia, STAT3 activation was potentially involved in TKI resistance and resulted in a worse prognosis." (PMID 39068158, 2024). "FAPM is a synthetic β-methoxyacrylates compound, which has been identified as a potent inhibitor of STAT3 activation and exhibits salutary effects when used in the treatment of myeloid leukemia." (PMID 38398568, 2024). "Although FAPM acts as a STAT3 activation inhibitor when used in the treatment of human myeloid leukemia cell lines in our previous study." (PMID 38398568, 2024). "Honokiol inhibits both constitutive and inducible STAT3 activation and reduces the mRNA expression of STAT3 target genes (Bcl-2, cyclin D1, and survival) in myeloid leukemia cells in a concentration-dependent manner." (PMID 34539403, 2021). "Of note, we are the first to demonstrate that through the aberrant phosphorylation of the four serine sites, stathmin mediates the role of PRL-3 in myeloid leukemia progression via targeting STAT3 signaling." (PMID 31546234, 2019). "In order to better recognize the influence of STAT3 pathway on PD-1 ligand expression in myeloid leukemia cells, STAT3 activity was modulated in THP-1, which was selected as a representative cell line according to the results obtained in the previous assays." (PMID 31406210, 2019). "In myeloid leukemia cells under steady state conditions, STAT3(Tyr705) phosphorylation (pSTAT3) was negligible, indicating no constitutive activation of this pathway." (PMID 31406210, 2019). "Through the phosphorylation of the four serine sites, stathmin mediated the role of PRL-3 in myeloid leukemia progression via targeting STAT3 signaling." (PMID 31546234, 2019). "Intriguingly, the extended exposure to IFN-γ prolonged the activation of STAT3 and upregulated its mRNA and total protein expression in myeloid leukemia cells." (PMID 31406210, 2019). "BMX is expressed in hematopoietic progenitor cells and myeloid leukemias and has been found to mediate STAT3 activation and subsequent transformation by Src." (PMID 26624983, 2016). "Further, LIFr is required for STAT3 activation to induce myeloid leukemia cell differentiation and growth arrest; the cytoplasmic domain of LIFr is capable of STAT3 signal transduction even when LIFr forms a homodimer." (PMID 26329521, 2015). "Similarly, constitutive activation of STAT3 and STAT5 are common events in myeloid leukemia and have previously been implicated in resistance to TKIs." (PMID 26547689, 2015). "Myeloid leukemias are often characterized by hyperphosphorylation of STAT3 and STAT5." (PMID 24952416, 2014). "Our data demonstrate a role of STAT3 in regulation of mdr1 gene expression in myeloid leukemia and suggest that STAT3 may be a promising therapeutic target for overcoming MDR resistance in myeloid leukemia." (PMID 21677772, 2011). "Overall, in myeloid leukemia cells, stattic not only abrogated the IFN-γ-induced STAT3 activation but also interfered with STAT1 phosphorylation." (PMID 31406210, 2019). "Moreover, our study was the first to provide evidence that silencing PRL-3 increased the phosphorylation level in Ser16, Ser25, Ser38, and Ser63 of stathmin, and in turn inhibited the STAT3 and STAT5 signaling in myeloid leukemia cells." (PMID 31546234, 2019). "As a specific example, STAT3 has been shown to differentially regulate the mRNA expression of BATF in myeloid leukemia but not in normal condition." (PMID 27145341, 2016).
prostate (23 papers, 2008 to 2026). "Meanwhile, we found that AZ505 blocked cisplatin-induced phosphorylation of NF-κB and STAT3, two transcription factors associated with kidney inflammation during AKI." (PMID 36046818, 2022). "Silencing of mda-9 decreases the activation of STAT3, which is an established regulator of prostate tumorigenesis and metastasis, as well as the transcription of self-renewal genes." (PMID 31878027, 2019). "STAT3 S727 phosphorylation was previously studied in prostate carcinogenesis and was shown to promote cell survival and cell invasion." (PMID 30065235, 2018). "Consistent with the repression of STAT3 pathway, which are highly relevant to bladder carcinogenesis, the suppression of STAT3 was further confirmed by the reduction of its downstream targets, such as Bcl-2, Bcl-xL and Mcl-1, at both mRNA and protein levels." (PMID 25849286, 2015). "Taken together, these findings demonstrated the important roles of the CXCL10/CXCR3 axis in modulating the JAK/STAT3 pathway and inducing neuroinflammation to mediate pain in chronic prostatitis, and targeting the NGF/TrKA pathway showed therapeutic efficacy in pain treatment in chronic prostatitis." (PMID 39718951, 2025). "However, the relationship between the CXCL10/CXCR3 axis and the JAK/STAT3 pathway in neuroinflammation and pain in chronic prostatitis was unknown." (PMID 39718951, 2025). "This study demonstrated the important roles of the CXCL10/CXCR3, JAK/STAT3 and NGF/TrKA pathways in neuroinflammation and pain in chronic prostatitis, which provided novel therapeutic targets for pain management in chronic prostatitis." (PMID 39718951, 2025). "The STAT3 signaling pathway and the apelin axis (apelin receptor, APLNR- and ligands, -apelin and/or -elabela), participate in the processes of kidney inflammation and fibrosis and both may be involved in muscle wasting during CKD." (PMID 42016932, 2026). "Because STAT3 was regulated by the JAK, we proposed that the JAK/STAT3 pathway may be downstream of the CXCL10/CXCR3 axis to induce spinal macrophage recruitment and pain in chronic prostatitis." (PMID 39718951, 2025). "Hence, the JAK/STAT3 pathway in spinal macrophage may play an important role in the CXCL10/CXCR3 axis‐induced neuroinflammation and mediate pain response in chronic prostatitis." (PMID 39718951, 2025). "STAT3 is a cytoplasmic transcription factor responsible for transcription of a myriad of genes involved with the cell cycle, apoptosis, and migration and STAT3 activation in responses to cytokines and upstream influences like EGFR, plays important roles in genitourinary cancers, including RCC." (PMID 37355607, 2023).
Chronic colitis (22 papers, 2013 to 2025). A chronic inflammatory disease of the large intestine (colon, cecum and rectum). "In contrast, the neutralization of IL-17A alleviated chronic colitis in mice with STAT3-deficient Treg cells and decreased innate immune colitis after H. hepaticus infection." (PMID 36532769, 2022). "Various studies show that myeloid cell-specific STAT3 deficiency results in enhanced inflammation and chronic colitis as a consequence of a decrease in PMN-MDSCs and linked herewith a decrease in suppressive cytokines (e.g. IL-10), an increase in pro-inflammatory cytokines (e.g. IFN-γ) and iNOS." (PMID 27029037, 2016). "We provided compelling evidence that the novel synthetic neuroactive peptide SVHRSP alleviates DSS-induced chronic colitis via the α7nAChR-mediated JAK2/STAT3 signaling pathway." (PMID 41300453, 2025). "The results showed that extracellular signal-regulated kinase (ERK), signal transducer, and activator of transcription 3 (STAT3) and p65 pathways were activated in chronic colitis." (PMID 33995655, 2021). "IL-6/STAT3 was also demonstrated to be involved in metabolic reprogramming, to promote the progression from chronic colitis to CRC, and the COX-2/PGE2 pathway was also shown to contribute to inflammation and carcinogenesis in IBD." (PMID 31523496, 2019). "Excessive activation of STAT3 mediated by increasing IL-6 enhances the expression of antiapoptotic factors such as Bcl-2, which contributes to the sustainability of chronic colitis." (PMID 30498394, 2018). "The Breg subset characterized by increased CD1d expression was first identified in a mice model of chronic colitis in which CD1dhi B cells produced IL-10 and suppressed the progression of intestinal inflammation through the repression of IL-1 and STAT3 activation in a CD1d-dependent manner." (PMID 24019869, 2013). "Besides its effects on IECs and ISCs, IL-22 facilitates the production of mucus-associated protein (Muc) by goblet cells via induction of signal transducer and activator of transcription 3 (STAT3), thereby promoting the formation of mucus layer and attenuating chronic colitis." (PMID 41467015, 2025). "Thus, it is very likely that myeloid cells expressing gankyrin play an indispensable role in the development of chronic colitis and CAC through the enhancement of pro-inflammatory cytokine responses, activation of STAT3 and MAP kinases, and finally expression of cancer stem cell markers." (PMID 28160571, 2017).
Hodgkins lymphoma (22 papers, 2010 to 2024). A heterogeneous group of malignant lymphoid neoplasms of B-cell origin characterized histologically by the presence of Hodgkin and Reed-Sternberg (HRS) cells in the vast majority of cases. "In a subset of Hodgkin Lymphoma survivors, therapy-related STAT3 mutations were detected that potentially also impact on T cell biology." (PMID 39613747, 2024). "Expression of PD-L1 by tumor cells and effect of anti-PD-1 immune therapy has been clearly demonstrated in Hodgkin’s lymphoma, a tumor which is constantly associated with both NF-κB and STAT3 activation." (PMID 31382969, 2019). "We report the evaluation of a next generation STAT3 ASO (AZD9150) in a non-Hodgkin’s lymphoma population, primarily consisting of patients with DLBCL." (PMID 30446007, 2018). "Another analogue of tyrphostin, AG17, inhibited STAT3 phosphorylation and induced apoptosis in classical Hodgkin lymphoma cells." (PMID 24199193, 2013). "STAT3 can be activated by the phosphorylation of its tyrosine and serine residues after receiving signals from upstream regulators, and the activation of STAT3 inhibits apoptosis of different classical Hodgkin lymphoma cell lines." (PMID 34628473, 2021). "Similarly, previous studies have shown that IL-21 attracts regulatory T-cells via up-regulation of macrophage inflammatory protein-3α and protects cells from apoptosis via activation of STAT3 signaling pathways in IL-21R+ Hodgkin lymphoma cells." (PMID 30728806, 2019). "This analysis highlighted that many KEGG Hodgkin lymphoma pathway genes are jointly induced by TES1 and TES2 signaling in LCLs, including CCL22, BCL3, cRel, IRF4, STAT3, STAT6, and CD70, each of which has prominent roles in Hodgkin lymphoma pathogenesis." (PMID 38009935, 2023). "The Hodgkin lymphoma cell line HDLM-2 has been demonstrated to show constitutive phosphorylation of JAK1 and JAK2, and STAT1, STAT3, STAT5 and STAT6." (PMID 26131691, 2015). "Aberrant STAT3 activation has been documented in MM, Hodgkin's disease, anaplastic lymphoma kinase-positive (ALK) DLBCL, and activated B-cell (ABC) DLBCL, in which JAK2/STAT3 inhibitors trigger arrest and apoptosis." (PMID 20433747, 2010). "Among the 10 Hodgkin's lymphoma patients, none (0%) showed expression of STAT3, while all 10 (100%) exhibited no expression of STAT3." (PMID 38817669, 2024). "STAT3 is a transcription factor which is activated via various signaling transduction pathways or Epstein-Barr virus (EBV) infection and plays an oncogenic role in lymphoid malignancies including Hodgkin lymphoma (HL)." (PMID 35884913, 2022). "In fact, while constitutive phosphorylation of STAT6 is known to be a distinctive feature of classical Hodgkin’s lymphoma, constitutive STAT3 activation is commonly encountered in both Hodgkin’s and non-Hodgkin’s lymphoma patients." (PMID 23593269, 2013). "In particular, ODZ17690 specifically inhibited the tyrosine phosphorylation of STAT3, but not that of other STAT and JAK family proteins in human Hodgkin’s lymphoma cells." (PMID 31684051, 2019).